IL10 (interleukin 10)
Diseases named in the same sentence as IL10 in open-access papers (continued):
Sharing a sentence is not in itself a finding about the gene and the disease.
malaria (continued). "Next, we showed negative correlations between the number of previous malaria episodes and the inflammatory disturbance detected during the current infection, except for, again, IL-10 MDP levels." (PMID 34727121, 2021). "The mean serum IL-10 levels of children without malaria, with mild, moderate and severe malaria was 321 ± 52 pg/mL, 815 ± 105 pg/mL, 842 ± 121 pg/mL and 935 ± 115 pg/mL, respectively." (PMID 35223394, 2021). "Thus, IL-10 is critical for promoting the optimal accumulation and B cell helper function of GC-TFH cells during experimental malaria." (PMID 33529242, 2021). "IL-10 responses to EBV and malaria antigen were comparable for Kisumu and eBL children; however, Nandi children had significantly higher CD4+ and CD8+ T cell IL-10 responses to malaria (typically an acute infection in this study population) compared to EBNA1." (PMID 34771539, 2021). "To address the potential effects of IL-10 on TFH development and function during experimental malaria, we first evaluated whether either CXCR5intPD-1int TFH or CXCR5hiPD-1hi GC-TFH responses were impaired in Plasmodium-infected Il10-/- mice." (PMID 33529242, 2021). "Here, we significantly extend this research by optimizing a blood-stage liposomal vaccine using the P. yoelii rodent malaria model and interrogating the immune response to identify CD4+ T cells, IFN-γ, TNF, and IL-10 as critical mediators of protective immunity." (PMID 34663097, 2021). "Conversely, the present results were different from the previous findings in an area with unusable malaria transmission in Sudan, where higher levels of IL-4 and IL-10 in the non-infected group was reported." (PMID 33422078, 2021). "Participants with asymptomatic malaria had also lower IFN-γ and IL-10 responses after Salmonella Typhimurium stimulation, while monocyte cytokines (IL-1β, IL-6, TNF-α) were not statistically different between slide negative participants and participants with asymptomatic malaria." (PMID 34177883, 2021). "IL-10 was elevated in individuals with multiple infections compared to ones with first time malaria; however, the elevation was not significant." (PMID 32256470, 2020). "In mouse malaria, increased levels of IL-10 have been associated with development of nontyphoidal Salmonella (NTS) bacteremia, suggesting that IL-10 suppresses mucosal inflammatory responses to invasive NTS." (PMID 32958528, 2020). "Among the severe malaria cases, TGF-β content was inversely correlated with the pro-inflammatory cytokines IFN-γ and IL-6, but perplexingly also the anti–inflammatory cytokine IL-10." (PMID 32043415, 2020). "In a study of acute-phase malaria in young children in Gabon, patients with severe malaria had significantly lower IL-12(p40/p70) and IFN-γ compared to matched controls with mild malaria; in addition, TNF and IL-10 were significantly higher in severe malarial cases." (PMID 31234875, 2019). "Although IL-10 is a promising target for immune modulation, it is not the only such target for trying to improve outcomes in malaria." (PMID 30809232, 2019). "This augmented production of IL-10 alongside IL-4 heightened levels can directly downregulate key proinflammatory cytokines such as TNF-α, and thus have a protective effect against severe malaria presentations." (PMID 31233500, 2019). "In a study of malaria infection of children in Mali, severe malaria cases, in comparison with matched healthy controls, showed higher levels of IL-6, IL-10, TNF, IL-12(p70), and IL-6 and IL-10 were higher in severe cases in comparison with matched uncomplicated malaria controls." (PMID 31234875, 2019). "BLIMP1-mediated IL-10 production by Tr1 cells was recently reported in experimental malaria, and BLIMP1-dependent IL-10 production by Tr1 cells protected against IFNγ-dependent, TNF-mediated splenic tissue damage, but also limited the control of P. chabaudi AS blood parasitemia." (PMID 30809232, 2019).
malaria (continued). "More recently, IL-10-producing Th1 (type 1 regulatory; Tr1) cells were found to develop relatively quickly in healthy volunteers participating in controlled human malaria infection (CHMI) studies and children living in malaria-endemic areas." (PMID 30809232, 2019). "A significantly higher level of IFN-γ, TNF-α, IL-6, and IL-10 were expressed by co-infected cases than malaria cases, except for TGF-β which did not vary significantly." (PMID 31687034, 2019). "It has been reported that imbalance of cytokines such as tumor necrosis factor alpha (TNF-α), interleukin-6 (IL-6), IL-10 and interferon gamma (IFN-γ) resulting from malaria related-inflammation can induce changes in iron absorption and distribution (iron delocalization)." (PMID 31760954, 2019). "Also, elevated levels of TGF-β, TNF-α, IL-10, and IL-1β were found in cerebral malaria, while IL-2, IFN-γ, IL-5, IL-6, and IL-12 were only increased in mild malaria." (PMID 31878288, 2019). "However, a case control study in an African population with mild or severe malaria showed that both IL-10 and TNF-α were elevated in severe malaria and positively correlated with parasitemia." (PMID 30809232, 2019). "Recruited infants were thoroughly examined, and infants who were found to have clinical malaria episodes did not have other diseases at the time of blood sample collection for determination of IL-10 and IFN-γ." (PMID 30154871, 2018). "The role of inflammatory cytokines increased by the absence of IL-10 has been studied extensively in the Plasmodium chabaudi mouse model of severe malaria." (PMID 29866139, 2018). "IL-10 is known to be anti-inflammatory, such that it antagonizes the effects of IFN-γ and it is a major mediator for the production of acute phase reactants in the pathogenesis of malaria." (PMID 30154871, 2018). "We measured Pf-specific IFNγ-, IL10-, and TNFα-producing CD4 T-cell responses by multi-parametric flow cytometry in 265 children aged 6 months to 10 years enrolled in a longitudinal observational cohort in a high malaria transmission site in Uganda." (PMID 29097996, 2017). "In a study from Kenya, children with severe malaria (the type of severe malaria was not specified) had higher IL-10-to-TNF-α ratios than did children presenting with mild disease." (PMID 28122790, 2017). "As these other markers could not be included in the model, it is unclear whether the combination of IL-10 and sTNF-RII is sufficiently specific for diagnosing malaria." (PMID 29255607, 2017). "IFN-γ production by non-Vγ9 γδ T cells was also found in the JHCs with no history of malaria, although no proliferation of non-Vγ9 γδT cells or IL-10 production was observed." (PMID 28769886, 2017). "The data presented here demonstrate that high levels of the circulatory pro‐inflammatory, TNF‐α, and IL‐6, are indicators of malaria severity, whereas anti‐inflammatory cytokine IL‐10 level does not differentiate SM and MM cases." (PMID 27042299, 2016). "It is highly likely that the strong antigen exposure and the cytokine milieu during acute malaria activates the IFNγ to IL10 switch, which serves as a negative feedback loop to prevent overwhelming inflammation and tissue damage." (PMID 27802341, 2016). "In addition, the significant multivariate correlation of EPO, hemopexin and total heme with TNF-α, IL-10, IP-10 and MCP-1 suggests the implication of EPO in the complex network of factors of the immune system influenced by heme during severe malaria." (PMID 27441662, 2016). "All these biomarkers were lower in the second samples confirming the induction of different types of immune mediators including growth factor (G-CSF), inflammatory (TNFα, IL-1α, IP-10), anti-inflammatory (IL-10) and chemokines (IL-8, MCP-1) during immune response to malaria." (PMID 27168977, 2016). "Of note, host cytokines such as IL-10 and IFN-γ could profoundly affect the malaria parasite-specific IgG3 and IgG4." (PMID 26999435, 2016).
malaria (continued). "In this study, we demonstrate that O. volvulus-infected individuals, residing within co-endemic areas of malaria in Ghana, presented increased IL-6, TNF-α and IL-10 production in response to the P. falciparum-derived antigen MSP-1 when compared to uninfected individuals." (PMID 25889652, 2015). "Lastly, higher IL-10 levels were found in malaria-exposed, non-sensitized newborns compared to sensitized, unexposed newborns, with this phenotype persisting during childhood." (PMID 26698578, 2015). "The anti-inflammatory response during malaria also implies the receptor CD163 which scavenges the complex haemoglobin:haptoglobin, allows heme degradation by HO-1, avoids tissue damage, and facilitates IL-10 secretion." (PMID 26385579, 2015). "Since none of our patients presented severe or complicated malaria, the higher serum levels of IL-6 and IL-10 seem to suggest an attempt of IL-6 to induce mechanisms that control the parasite and IL-10, in its turn, to control the inflammation." (PMID 24741587, 2014). "For malaria infected individuals (M and CI) the profile was high levels of IL-1β, IL-6, TNF-α IL-10, and CRP and decreased levels of IL-17A while for malaria negative individuals (IP and UN) the profile was high levels of IL-17A, NO and decreased levels of IL-10 and CRP." (PMID 25309052, 2014). "Both IL-10-producing CD4+ T cells and IFNγ-producing CD4+ T cells were present at higher frequencies among children with a higher prior incidence of malaria (≥2 episodes ppy) than among those with a lower prior incidence (<2 episodes ppy, P<0.001 and P = 0.02, respectively)." (PMID 24415936, 2014). "We magnetically isolated CD4+ T cells that had been collected after the resolution of febrile malaria and found that they failed to produce IL-10 in response to iRBC stimulation in the absence of antigen-presenting cells." (PMID 24743880, 2014). "The similar levels of IL-10 detected in P. yoelii infection and co-infection indicated that the malaria parasites, rather than S. Typhimurium, were eliciting IL-10 production in this model." (PMID 24787713, 2014). "Under both conditions iRBC-inducible IL-10 production by CD4+ T cells was restored to similar levels, suggesting that the in vivo conditions during acute febrile malaria shape the functional response of CD4+ T cells in a manner that is independent of the in vivo conditioning of APCs." (PMID 24743880, 2014). "In the group of individuals presenting with severe non-lethal malaria, parasitaemia displayed significant positive associations with TNF, sTNF-RI, IFN-γ, IL-10, CXCL9, CXCL10, SOD-1 and HO-1, while negatively correlated with the chemokines IL-8 and CCL2." (PMID 23433077, 2013). "Under natural exposure conditions, IFN-γ CD4+ T cell responses to P. falciparum appeared to be short-lived (half-life of 3.3 years) in areas of unstable malaria transmission, whereas IL-10 CD4+ T cells did not appear to decline for 6 years." (PMID 23967342, 2013). "Support for this modulatory hypothesis comes from the description that IL-10 and IL-4 can directly down regulate pro-inflammatory cytokines such as IL-6, TNF and IL-1β and prevent severe forms of malaria." (PMID 23433077, 2013). "Nevertheless, immigrants and travelers with malaria had higher IFN-γ, IL-6 and IL-10 compared to those without malaria." (PMID 23967342, 2013). "IL-10, an immunoregulatory cytokine, is extensively reported in relation to malaria immunopathogenesis and not so much associated with immunity." (PMID 22280502, 2012). "The absence of immunoassay data within this study and severe malaria phenotypes observed in the participants was a limitation to demonstrating the role of IL10 in mitigating Plasmodium infections." (PMID 22615793, 2012). "Concentrations of IL-10 (31.6 pg/mL) were significantly reduced (P < 0.05) in sera samples from malaria positive placentas compared to concentrations in sera samples from malaria negative placentas (72.5 pg/mL)." (PMID 26623293, 2012).
malaria (continued). "In particular, IL-10 (intracellular and plasma) and MCP-1 were more consistently associated with incidence of malaria, and this association was not explained by age or previous episodes." (PMID 22280502, 2012). "Children with malaria had decreased levels of apoA1 and albumin, but high levels of IL-10 when compared to children without malaria." (PMID 23208374, 2012). "We did not see marked differences in Th2 cytokines (e.g., IL-4, IL-10) which have been shown to be produced by inducible Tregs and limit malaria pathogenicity." (PMID 22348117, 2012). "Malaria-naïve U.S. adult controls had no detectable increases in expression of TGF-β or IL-10 from Tregs following exposure to either antigen." (PMID 22348117, 2012). "We found little evidence of malaria-specific IL-10 responses by flow cytometry after 24 hrs co-culture with PfSE, PHA or PPD." (PMID 21347351, 2011). "Moreover, corroborating the reduction in the pro-inflammatory profile, we discovered higher expression of IL-10, TGF-β1 and IL-27 in both lymph nodes in the EAE-malaria mice relative to the EAE-alone mice." (PMID 21464982, 2011). "The effects of polymorphisms in a number of genes, including β-globin, G6PD, TNF-α, IFN-γ, CD36, ICAM-1, IL10, IL4R, and LTA, upon the clearance of malaria parasites in African individuals was investigated across five large association studies from Burkina Faso, Cameroon, Kenya, Mali, and Sudan." (PMID 21867552, 2011). "Several studies suggest that the balance between pro- (TNF-α, IFN-γ, IL-8) and anti-inflammatory (IL4, IL-10, TGF-β) cytokines determines the degree of malaria parasitaemia, the level of anaemia, the clinical severity, the presentation, and/or the outcome of infection." (PMID 21867552, 2011). "The overall Th2/Th1 balance, the homeostatic role of interleukin 10 and TGF-β as modulators of the immune response, and the role of the CD23/NO pathway in reducing sequestration are additional possible mechanisms of protection against severe malaria." (PMID 20574512, 2010). "Moreover, we have identified a population of FOXP3−, CD45RO+, CD4+ T cells which co-produce IL-10 and IFN-γ and which are more prevalent in children with uncomplicated malaria than in those with severe disease." (PMID 19343213, 2009). "By contrast, distinct populations of IL-10+ and IFN-γ+ cells were seen among the PI-stimulated cells from children with acute severe or uncomplicated malaria, with a small but easily distinguishable population of cells (approx 1% of all PBMC) producing both cytokines simultaneously (right plot)." (PMID 19343213, 2009). "While these studies suggest the involvement of IL-10 and TGFβ in CD4+CD25+ Treg induction during malaria, no causal connection has been proven to date." (PMID 19680449, 2009). "Malaria antigen–driven IL-10 production alone was not considered a criterion for fetal priming because non-T cells can generate IL-10." (PMID 19636353, 2009). "However, the exact role of IL-10 and TGF-β appears to vary between infections with different malaria species and strains, depending on the timing of cytokine production in relation to disease progression." (PMID 18401464, 2008). "The plasma levels of TNF-α and IL-10 were comparable to those in normal Ghanaian children without symptoms of malaria or detectable parasitaemia." (PMID 16321150, 2005). "Other markers tested were not significantly enriched for IL-10 on malaria-experienced individuals." (PMID 40337867, 2025). "Among both children less than 5 years, and those from 5 to 12 years, TNF‐α (p < .001), IFN‐ɣ (p < .001), IL‐1β (p < .001), IL‐6 (p < .001), GM‐CSF (p < .001), and IL‐10 (p < .001) levels were elevated in the participants with malaria compared with the apparently healthy children without malaria." (PMID 39240033, 2024).
malaria (continued). "Malaria‐infected children had higher tumor necrosis factor alpha (TNF‐α) (p < .001), interferon‐gamma (IFN‐ɣ) (p < .001), interleukin (IL)‐1β (p < .001), IL‐6 (p < .001), granulocyte macrophage‐colony stimulating factor (GM‐CSF) (p < .001), and IL‐10 (p < .001) levels than controls." (PMID 39240033, 2024). "This study found increased plasma levels of proinflammatory cytokines: TNF‐α, IFN‐ɣ, IL‐1β, IL‐6, and GM‐CSF, and the anti‐inflammatory cytokine IL‐10 in malaria‐infected children than the controls without malaria, and the levels were higher in participants with high parasitemia." (PMID 39240033, 2024). "The proinflammatory cytokines: TNF‐α (p < .001), IFN‐ɣ (p < .001), IL‐1β (p < .001), IL‐6 (p < .001), GM‐CSF (p < .001), and the anti‐inflammatory cytokine IL‐10 (p < .001) levels were significantly higher in malaria‐infected males and females than in their counterparts without malaria." (PMID 39240033, 2024). "In this context, it is possible to speculate that during EBV reactivation, the virus induces high secretion of cytokines such as TNF-α, IL-12p40, IL-10, and IFN-γ, which could exacerbate the immune response to malaria and contribute to uncontrolled proliferation of the parasite." (PMID 39133703, 2024). "Notably, complement genes (C1QA, C1QB, C1QC), apoptotic genes (PDL1, PDL2, APOL1, APOL2, FAS), inflammatory caspases (CASP1, CASP5), TLR pathway genes (TLR1, TLR4, TLR5, TLR8), cytokines (IL6, IL10), and granzyme (GZMB) were among the genes upregulated during symptomatic malaria." (PMID 39161730, 2024). "Furthermore, previous studies showed higher IL-10/TNF-α levels in children with severe malaria than in those with a non-severe disease, and these cytokines were also higher in patients who died than in those who survived." (PMID 36668942, 2023). "Plasma levels of IL-10 in pregnant women with malaria have been shown to be higher than those in uninfected women, and levels of malaria non-specific, IFNγ and IL-10 co-producing cells were elevated in pregnant versus non-pregnant women living in Papua New Guinea." (PMID 37634385, 2023). "Finally, 19 studies comparing IL-10 levels between severe and non-severe malaria were included in the quantitative syntheses." (PMID 36668942, 2023). "The difference in the IL-10 levels between patients with severe and non-severe malaria in the studies from different geographical areas might be attributed to an age group variance." (PMID 36668942, 2023). "Fourth, the difference in the IL-10 levels between patients with different severe complications of malaria could not be analyzed due to the incomplete and limited information from the included studies." (PMID 36668942, 2023). "Thus, we performed a systematic review and meta-analysis of the available studies that compared the IL-10 levels in patients with severe malaria and in those with non-severe malaria." (PMID 36668942, 2023). "The production of IL-10 by Th1 cells has emerged as an important mechanism for dampening T cell and APC activation in the face of intractable infection, including in patients with visceral leishmaniasis, active pulmonary tuberculosis, primary HIV infection, and malaria (in children in Gambia)." (PMID 36594463, 2023). "Therefore, we performed a systematic review and meta-analysis to determine the difference in IL-10 levels between patients with severe malaria and those with non-severe malaria." (PMID 36668942, 2023). "Follow-up studies from this group demonstrated that both CD4+ T cells and CD8+ T cells from malaria-infected individuals adopted a Tr1-like phenotype and cytokine profile, illustrated by high expression of LAG-3 and co-inhibitory receptors accompanied by production of IL-10, IFN-γ, and granzyme B." (PMID 36389662, 2022).